SNHG5 (small nucleolar RNA host gene 5)
Diseases named in the same sentence as SNHG5 in open-access papers (continued):
Sharing a sentence is not in itself a finding about the gene and the disease.
tumor (continued). "For instance, SNHG5 is a tumor suppressor in GC, SNHG8 predicts a poor prognosis in GC patients and SNHG17 induces the development of GC." (PMID 31808752, 2019). "Meanwhile, xenograft tumor model showed knockdown of SNHG5 inhibited tumor growth and metastasis in vivo." (PMID 30166525, 2018). "Specifically, SNHG5 expression was remarkably higher in larger tumors and more advance stages of tumor development." (PMID 30166525, 2018). "Functionally, SNHG5 promotes tumor growth and metastasis by activating Wnt/β-catenin pathway and inducing epithelial to mesenchymal transition (EMT)." (PMID 30166525, 2018). "The tumor growth curve and tumor weight suggested that SNHG5 knockdown effectively suppressed tumor growth compared with the NC group." (PMID 30166525, 2018). "Introduction of miR-212-3p mimics or inhibitors reverses SNHG5 overexpression or silences the exerted tumor promoting or suppressing effect." (PMID 30250399, 2018). "Results from clinical studies indicated that aberrant expression of SNHG5 was closely associated with the clinicopathological parameters of HCC, such as Tumor size, HBV infection, histologic grade, TNM stage, and portal vein tumor thrombus (PVTT)." (PMID 30166525, 2018). "Profiling a large set of CRCs, we identified the cytoplasmic lncRNA SNHG5 as significantly overexpressed in tumours." (PMID 28004750, 2016). "The correlation found in CRC samples was further confirmed by analyzing SPATS2 levels in the xenograft tumours, where knockdown of SNHG5 resulted in a significant decrease in SPATS2 mRNA levels." (PMID 28004750, 2016). "Depletion of SNHG5 induces cell cycle arrest and apoptosis in vitro and limits tumour outgrowth in vivo, whereas SNHG5 overexpression counteracts oxaliplatin-induced apoptosis." (PMID 28004750, 2016). "Several studies have demonstrated that SNHG5 promotes tumor progression by inducing EMT." (PMID 41550840, 2026). "Mechanistically, SNHG5 promotes tumor progression through multiple regulatory pathways." (PMID 41550840, 2026). "In contrast, SNHG3 and SNHG5 exhibit tumor-suppressive effects in some studies." (PMID 41234719, 2025). "Additionally, SNHG5 accelerates tumor progression by activating the NF-κB pathway via the miR-181c-5p/CBX4 axis." (PMID 41301542, 2025). "Therefore, SNHG5 is a promising potential therapeutic target for tumours and a reliable prognostic biomarker." (PMID 38475928, 2024). "Additionally, high SNHG5 expression predicts advanced TNM staging, increased susceptibility to distant metastasis, increased tumour diameter, and decreased histological grade." (PMID 38475928, 2024). "Finally, several studies revealed that SNHG5 is highly expressed in tumour cells, while others revealed that SNHG5 is expressed at low levels in tumour cells, leading to inconsistent experimental conclusions." (PMID 38475928, 2024). "SNHG5 expression is typically increased in the majority of tumour tissues." (PMID 38475928, 2024). "Furthermore, the results from controlled clinical trials also revealed that higher expression of SNHG5 is significantly positively correlated with a smaller size of the tumor, earlier TNM stage, and clinical-pathological negative lymph node metastasis of LAD." (PMID 36711024, 2023). "Next, to the in vivo roles of SNHG5 in DLBC was also explored by the xenograft mice tumor models." (PMID 35154447, 2022). "Furthermore, increasing evidence indicated that SNHG5 played important regulatory roles in proliferation, migration, invasion and growth of various tumor cells." (PMID 34351577, 2022). "SNHG5 was involved in several tumor and nontumor diseases and is associated with clinical features, prognosis, drug sensitivity, and other factors regarding diagnosis and treatment." (PMID 36257404, 2022). "SNHG5 was one of the down-expressed genes in MCL tumor tissues based on WTS analysis." (PMID 36359790, 2022). "Moreover, low expression of SNHG5 was associated with an increased risk of LNM and larger tumor size in patients with PTC." (PMID 35338124, 2022).
tumor (continued). "First of all, the expression of SNHG5 in DLBC tumor samples and normal tissues were compared." (PMID 35154447, 2022). "SNHG5 also showed borderline significant decreases in tumor stages in luminal A/B subgroups." (PMID 34944924, 2021). "Additionally, SNHG5 has been shown to exert its tumour-promoting function through the sponging mRNA p27, which is reduced in BCa cells." (PMID 33968736, 2021). "The results suggested that knockdown of SNHG5 efficaciously inhibited tumour growth." (PMID 31292168, 2019). "Firstly, we examined the effect of SNHG5 on cell phenotype, knockdown of SNHG5 induced the reversion of mesenchymal like morphological feature into an epithelial phenotype in HepG2 cells.The rescue experiments was conducted to prove that SNHG5 promote tumor EMT by competitively binding miR-26-5p." (PMID 30166525, 2018). "We next employed a luminescent xenograft mouse model to query whether SNHG5 expression is required for tumour growth in vivo." (PMID 28004750, 2016). "In addition, the cytoplasmic localization and tumor-restricted overexpression of SNHG5 make it an attractive candidate for lncRNA-directed therapeutics, building on preclinical experience with antisense oligonucleotides against other oncogenic lncRNAs such as MALAT1." (PMID 41550840, 2026). "Finally, the effects of SNHG5 axis on the growth of DLBC tumor was examined by in vivo analysis." (PMID 35154447, 2022). "lncRNA small nucleolar RNA host gene 5 (SNHG5) was found acting as a competing endogenous RNA competitively binding with miR-26a-5p and thereby modulating the de-repression of downstream target GSK3β, functionally promoted tumor metastasis and induced EMT via activating Wnt/β-catenin pathway." (PMID 31555129, 2019). "Furthermore, SNHG5 induced tumor EMT by activating the Wnt/β-catenin pathway." (PMID 30166525, 2018). "Collectively, these data suggest that the functional impact of SNHG5 on EMT and Wnt/β-catenin signaling is tumor type–specific, likely determined by the cellular context, interaction networks, and microenvironmental cues." (PMID 41550840, 2026). "Consistently, the liver-to-body weight ratio, a surrogate marker of tumor load, was significantly elevated in the GNB2-overexpressing group and reduced upon Snhg5 silencing." (PMID 41550840, 2026). "Based on this evaluation, LINC00877, SLC25A5-AS1, ILF3-DT, LRRC75A-AS1, LINC00324, CD27-AS1, ZFAS1, SNHG5, MIR762HG, and SNRK-AS1 were the top significantly downregulated tumor suppressor candidates in MCL cases." (PMID 36359790, 2022). "These analyses revealed that WTS and qRT-PCR expression values correlate significantly across MCL tumor samples and reactive tonsil B-cell subset samples for both CCND1 and SNHG5." (PMID 36359790, 2022). "Thus, we speculated that SNHG5 might be critical for tumor metastasis." (PMID 30166525, 2018). "To further explore the interaction between SNHG5 and SPATS2, we investigated the SNHG5 and SPATS2 expression patterns in primary CRCs and mouse xenograft tumours." (PMID 28004750, 2016). "We provide evidence that SNHG5 expression regulates the survival of CRC cells and the progression of CRC tumour xenografts in a mouse model." (PMID 28004750, 2016). "SNHG5 (Small Nucleolar RNA Host Gene 5) is frequently overexpressed in various solid malignancies, including CRC, where its expression positively correlates with tumor size, metastatic burden, and pathological staging [,39]." (PMID 41550840, 2026). "Furthermore, combined OR data indicated that elevated SNHG5 expression was a predictor of advanced TNM staging, larger tumour size, easier distant metastasis, and poor histological grade." (PMID 38475928, 2024). "Similarly, all studied SNHGs are involved in EMT through activation of various athways including Notch-1, but in vivo experiments reveal a more crucial role in tumor growth and metastasis for SNHG1, SNHG3, SNHG5, SNHG12, and SNORA71A." (PMID 36139687, 2022).
tumor (continued). "Previous studies suggested that Wnt/β-catenin pathway play important role in tumor EMT, hence we speculated that SNHG5 induces EMT by activates Wnt/β-catenin pathway." (PMID 30166525, 2018). "SNHG5 levels were significantly reduced in the tumours following doxycycline treatment compared with the non-targeting control." (PMID 28004750, 2016). "Additionally, the expression of SNHG5, miR-205 and E2F3 in the tumours was detected." (PMID 31292168, 2019). "Importantly, suppression of SNHG5 expression not only exerts a strong anti-proliferative effect and induces apoptosis, impacting key survival pathways such as the STAT3 pathway in vitro, but also reduces tumour progression in vivo." (PMID 28004750, 2016). "Unlike the first two lncRNAs, the role of SNHG5 in tumors varies depending on gene copy variation (deletion or amplification), transcription factors, histone modification, or DNA methylation differences in gastric patients, it can either promote or suppress tumor growth." (PMID 37258567, 2023). "Importantly, we observed a significant negative effect on tumour growth following SNHG5 depletion." (PMID 28004750, 2016).
intestinal diseases (1 paper, 2021). "Dysregulation of SNHG5 plays a crucial role in intestinal diseases." (PMID 34334085, 2021).
kidney disease (1 paper, 2022). "Regarding nonneoplastic kidney disease, a recent study indicated that SNHG5 expression was elevated in HK-2 cells treated with HG, accompanied with decreased cell viability, increased apoptosis, and enhanced inflammatory cytokines and oxidative stress." (PMID 36257404, 2022).
psychiatric disease (1 paper, 2025). "Our results also showed that many psychiatric disease-associated remarkable genes, were upregulated (SLC35F1, SNHG5, and FAM118A) or downregulated (SLC26A3, SLC27A4, LINGO1, and RASGEF1B) in PBMCs of patients with WD." (PMID 40384935, 2025).
SNHG5 also shares sentences with these, for which no sentence is quoted: gastric adenocarcinoma (2 papers); lymphoma (2); psoriasis (2); B-cell chronic lymphocytic leukemia (1); brain glioma (1); brain tumor (1); cardiac hypertrophy (1); cardiomyopathies (1); chronic myeloid leukemia (1); colitis (1); digestive system cancer (1); esophageal cancer (1); esophageal squamous cell carcinoma (1); fibrosis (1); heart failure (1); ischemic stroke (1); laryngeal carcinoma (1); Nephroblastoma (1); neurological disorders (1); oesophageal cancer (1); oral cancer (1); renal cell carcinoma (1); Rett syndrome (1).